LINC02606 (long independently transcribed non-coding RNA 2606)
Gene: Long non-coding RNA gene on chromosome 1 (9,425,094 to 9,455,910, reverse strand). Ensembl gene ENSG00000284693.
Diseases named in the same sentence as LINC02606 in open-access papers:
LINC02606 is named in the same sentence as 1 disease in open-access papers, as found by Europe PMC text mining. Sharing a sentence is not in itself a finding about the gene and the disease. The quoted sentences say what the papers report.
viral infection (1 paper, 2021). "Knockdown of LINC02606 resulted in reduced expression of PTEN in both mRNA and protein level upon viral infection." (PMID 34804040, 2021).